RN7SKP204 (RN7SK pseudogene 204)
Gene: Miscellaneous RNA gene on chromosome 6 (13,547,704 to 13,548,013, forward strand). Ensembl gene ENSG00000202351.
Homologues: Orthologues: chimpanzee 7SK (95% identical), mouse Gm54931 (65% identical). Paralogues in human: RN7SKP255 (78% identical), RN7SKP176 (77% identical), RN7SKP71 (77% identical), RN7SKP79 (77% identical), RN7SKP90 (76% identical), 7SK (76% identical), RN7SKP1 (76% identical), RN7SKP180 (76% identical), RN7SKP250 (76% identical), RN7SKP37 (76% identical), RN7SKP230 (75% identical), RN7SKP9 (75% identical), and 284 more.